TXNIP (thioredoxin interacting protein)
Diseases named in the same sentence as TXNIP in open-access papers (continued):
Sharing a sentence is not in itself a finding about the gene and the disease.
cancer (continued). "TXNIP has attracted attention in drug development owing to its multiple functions and involvement in metabolic disorders, inflammatory diseases, neurodegenerative diseases, and cancer." (PMID 36059548, 2022). "TXNIP participates in metabolic reprogramming and induces oxidative stress in various cancer cells." (PMID 36139416, 2022). "TXNIP is useful in preventing the progression of various cancers." (PMID 36366411, 2022). "TXNIP has attracted considerable attention regarding drug development owing to its multiple functions and involvement in metabolic disorders, inflammation, neurodegenerative disorders as well as cancer." (PMID 33803178, 2021). "In contrast, TXNIP was underexpressed in most cancers, leading to high cell proliferation." (PMID 34500775, 2021). "In addition, knockdown of TXNIP and circDCUN1D4 reduced the cancer cell migration induced by circDCUN1D4 silencing." (PMID 33425493, 2021). "Second, while activating TXNIP may be beneficial in cancer, data accumulated in the last few years strongly suggests that this would have a deleterious impact on lipid and glucose metabolism, with an increased risk of developing diabetes." (PMID 33846376, 2021). "TXNIP may therefore be of basic and clinical significance for finding novel molecular targets that can facilitate the diagnosis and treatment of malignant tumors." (PMID 33194655, 2020). "Subsequent studies fostered the role of TXNIP in cancer pathophysiology and therapy." (PMID 33081035, 2020). "TXNIP expression in cancers of the endocrine glands and genital tracts." (PMID 33194655, 2020). "Previous cancer studies have reported that TXNIP is regulated by miR-373, miR-411, and miR-224." (PMID 32013265, 2020). "TXNIP was commonly silenced in cancer cells due to genetic or epigenetic events." (PMID 32328125, 2020). "A number of studies have shown that TXNIP expression is decreased in various cancer cells." (PMID 32511893, 2020). "Because protein synthesis inhibitors are emerging as potential cancer therapeutics, we tested whether blocking protein synthesis induced TXNIP expression in cell lines with different oncogenic lesions." (PMID 33292639, 2020). "Recent studies have revealed that TXNIP is silenced in a wide range of cancer cells." (PMID 32511893, 2020). "In the specific case of the TXNIP gene, our data suggest that high TXNIP levels in LS may account for cancer protection in this disease by maintaining cellular homeostasis." (PMID 31208077, 2019). "Additional pathways that might be involved in cancer protection in this pathology include the ubiquitin complex and mitochondrial enzymes, including TXNIP." (PMID 31320996, 2019). "TXNIP is frequently downregulated in cancer by genetic and epigenetic mechanisms." (PMID 31261735, 2019). "TXNIP is frequently silenced by genetic or epigenetic mechanisms in cancer cells." (PMID 31208077, 2019). "High TXNIP is anti-correlated with glucose uptake in human tumors and is a predictor of better overall survival in cancer patients, establishing the MondoA/TXNIP axis as an important prognostic factor in cancer." (PMID 30717828, 2019). "Dissection of the complex regulatory loops involving the IGF1 and TXNIP pathways could be of relevance to our understanding of physio-pathological processes as well as to our ability to personalize cancer protocols." (PMID 31208077, 2019). "In fact, TXNIP levels are differentially regulated by 1,25(OH)2D3 in different cancer cell lines." (PMID 29534438, 2018). "In early stage cancers without diffuse peritoneal dissemination, low TXNIP transcript was associated with poorer survival." (PMID 30479697, 2018). "This study describes the regulation of TXNIP expression by 1,25(OH)2D3 in different cancer models." (PMID 29534438, 2018). "Furthermore, screening TXNIP regulation by 1,25(OH)2D3 in multiple cancer cell lines of different tissue origins demonstrated either induction, reduction, or not change in TXNIP levels by treatment." (PMID 30181873, 2018).
cancer (continued). "The present work elucidates the mechanism of TXNIP function in cell cycle regulation and may contribute to the establishment of a new strategy of cancer therapy." (PMID 30410860, 2018). "The expression level of TXNIP is decreased in many types of cancer compared to the normal tissues." (PMID 29996811, 2018). "This non-canonical regulation prompted us to investigate whether 1,25(OH)2D3 is capable of inducing TXNIP expression in different cancer types, including those with silenced TXNIP expression." (PMID 29534438, 2018). "This work may facilitate the development of a new cancer therapy strategy that targets TXNIP as a key molecule inhibiting cancer cell growth via cell cycle blockade at the G1/S checkpoint." (PMID 30410860, 2018). "In addition to TXNIP, increased phosphorylation of eIF2α has also been shown, by several laboratories including ours, to mediate the cytotoxic effect of vorinostat on cancer cells." (PMID 27196668, 2016). "Therefore, as a major redox regulator, TXNIP has recently been proposed as a therapeutic target for cancer treatment." (PMID 25605021, 2015). "There is evidence that D-allose (present in leaves of Moringa) inhibits the growth of cancer cells at G1 phase (G1- cell cycle arrest) through specific thioredoxin interacting protein (TXNIP) induction and subsequent p27kip1 protein stabilization without exerting appreciable effects on normal cells." (PMID 26288313, 2015). "To evaluate the putative association between TXNIP and p27 with OS, we performed IHC staining against these proteins in malignant tumor and corresponding noncancerous tissues (NCTs) samples from 150 patients using a tissue microarray." (PMID 25605021, 2015). "However, little is known about the mechanism by which miR-373 decreases TXNIP to stimulate cancer metastasis." (PMID 26196741, 2015). "Given the well-recognized role of TXNIP to repress glucose uptake and glycolysis, we expect that amino acid deprivation may also affect glucose metabolism in cancer." (PMID 25849282, 2015). "In contrast, theconsistent inhibition of TXNIP by limited glucose availability in cancer cellsas well as in differentiated smooth muscle cells and non-differentia-ted stemcells, is indicative of a potential role of this gene in mediating theanti-aging action of calorie restriction." (PMID 20195491, 2009). "According to our findings, we can propose a model according to which the overexpression of WWP1 in AML blasts could lead to increased Trx activity through accelerated TXNIP degradation, thus lowering intracellular ROS levels and favoring survival of cancer cells." (PMID 39364720, 2025). "Additionally, glutamine deprivation or GLS1 inhibition represses glycolysis and lactate production in several cancer cells through upregulation of thioredoxin interacting protein (TXNIP) and phosphorylation of PFKFB3, potentially reducing lactate-induced differentiation of M2 macrophages." (PMID 41235226, 2025). "Notably, the dual role of ROS in cancer could partially be the reason for diverse functions of TXNIP in cancer." (PMID 37794178, 2023). "Furthermore, as TXNIP exists in nearly every cell and plays almost the same function in each cell, its expression may also indicate the prognosis of other cancers." (PMID 35450411, 2022). "Furthermore, TXNIP is implicated in many other pathways, including the HIF1α hypoxic pathway, the IL-dependent pathway, the B cell receptor (BCR) signaling pathway, and the NF-κB signaling pathway, all of which require empirical support to comprehend TXNIP’s role in cancer." (PMID 36366411, 2022). "Indeed, it is common for various types of cancers to downregulate TXNIP." (PMID 33228209, 2020). "Thus, downregulation of TXNIP would confer a transformative advantage in cancer progression." (PMID 33081035, 2020). "In this regard, TXNIP might be a potential target for anti-cancer drug development." (PMID 33233497, 2020).
cancer (continued). "Furthermore, the negative regulation of glucose transporters by 1,25(OH)2D3, as shown in the case of GLUT1 in cancer cells, may reduce glucose uptake and intracellular levels of glycolytic intermediates capable of inducing TXNIP expression." (PMID 29048387, 2017). "However, genetic alternations of TXNIP, such as deletion, translocation or somatic mutation, are not detected in these cancers." (PMID 26196741, 2015). "Additionally, re-expression of TXNIP leads to cell growth arrest and apoptosis in cancer." (PMID 21931799, 2011). "Analysis of the cancer genome atlas datasets confirmed an inverse correlation between GPR161 and TXNIP expression and showed that low TXNIP levels predicted poor overall survival." (PMID 41834581, 2026). "Further research is needed to define the broader function of the TXNIP-CAST interaction in development and to identify key regulators of their interaction in cancer cells." (PMID 40175348, 2025). "Further research into the interactions between TXNIP, CAST, and IL-24 is essential to better understand their roles in cancer." (PMID 40175348, 2025). "In most cancer species, the TXN and TXNRD1 high expression groups and the TXNIP low expression group had lower stromal and immune scores." (PMID 39744566, 2025). "For example, the N-terminus is sufficient to interact with KPNA2 for TXNIP’s localization to the nucleus, while the C-terminus of TXNIP is critical for interactions with COPS5, to inhibit cancer cell proliferation." (PMID 38727583, 2024). "Further support for both TXNIP and ARRDC4’s role in regulating GDF15 after the induction of ROS comes from a pan cancer meta-analysis assessing the impact of metformin (which has been reported to inhibit ROS) on gene expression." (PMID 39103698, 2024). "Another well-known α-arrestin, TXNIP, was first named as vitamin D3-upregulated protein 1 (VDUP1) after verification that its gene is a vitamin D3 target in cancer cells." (PMID 38270169, 2024). "In PDAC, TXNIP expression is upregulated in TAMs, and this is driven by KRAS activity in cancer cells." (PMID 37794178, 2023). "This correlation has been observed in cancer in which cell growth is promoted due to high levels of SELENOM and low levels of TXNIP." (PMID 38001759, 2023). "However, different studies in a variety of different cancers, utilising a variety of different techniques have reached different conclusions, suggesting that the role of TXNIP is complex in cancer and may have different implications depending on cancer type and stage of disease." (PMID 37794178, 2023). "We found significantly reduced levels of all three proteins in the cancer tissues when compared to the matching normal pancreatic tissues (p = 0.0112 for REDD1, 0.0095 for ATF4, and 0.0283 for TXNIP)." (PMID 38089448, 2022). "Hence, TXNIP may be a good target to treat cancers by increasing its level within cancer cells." (PMID 35450411, 2022). "miR-20b inhibits TXNIP, which is involved in the PI3K/AKT/mTOR pathway to promote the GC progression by mediating glucose uptake in cancer cells." (PMID 35450411, 2022). "In agreement with the present findings, BRG1 was found to promote TXNIP, CXCL11 and IL6 expression in GBM cancer stem cells, suggesting a broad role of these genes in the pro‐tumorigenic role of BRG1 in GBM." (PMID 33528916, 2021). "It has been found that the D-allose-mediated induction of TXNIP will promote the downregulation of the glucose transporter 1 (GLUT1), which is responsible for glucose uptake, preventing glucose absorption by cancer cells." (PMID 33808719, 2021). "miR-373 has been found to bind to the 3’UTR of thioredoxin interacting protein (TXNIP) and downregulate its expression, which activates HIF-1α to promote cancer progression." (PMID 35006436, 2020). "Among the up-regulated genes, we observe the proto-oncogene FOS62 as well as a set of other cancer-related genes such as HSPE1, TXN and TXNIP." (PMID 29434270, 2018).
cancer (continued). "MiR-373 suppresses TXNIP by binding to the 3′UTR of TXNIP, which in turn, induces cancer cell EMT and metastasis." (PMID 26196741, 2015). "Since no prior study had established a link between TXNIP and IL-24 in cancer development, we conducted further validation and functional assays of IL-24 due to its recognized role in cancer-specific cytotoxicity." (PMID 40175348, 2025). "Concomitantly, TXNIP destabilization in WWP1‐overexpressing leukemic cells would restrict its capacity to inhibit intracellular glucose transport and consumption, further contributing to the promotion of cancer cell survival and fitness." (PMID 39364720, 2025). "Furthermore, we find that TXNIP inhibits theactivation of the MAPK signaling pathway, thereby decreasing the malignant potential ofpancreatic cancer." (PMID 38229544, 2024). "The imbalance in TXNIP/TXN expression and stromal inflammation leading to increased level of ROS may explain the frequent development of precursor lesions and cancer in ESRD/ACRD kidney." (PMID 39020292, 2024). "In the case of TXNIP, decreased levels prevent the clearance of oxidative species within the cells, while reduced levels of CADM4 limit the interaction with the extracellular matrix in cancer cells." (PMID 37367050, 2023). "Bridging the links between TXNIP and the proteins histone deacetylases (HDAC) and p65 can prevent them from deactivating the growth-suppressive gene, as these proteins are responsible for bolstering cancer cell proliferation." (PMID 36366411, 2022). "eIF3a regulation of AMPK and glucose uptake in promoting cancer cell proliferation may work through TBC1D1 and TXNIP regulation of GLUT4 and GLUT1." (PMID 35595099, 2022). "Although TXNIP is a well-recognized glucose sensor and regulator in glucose metabolism in many types of cancers, its role in HCC has not been reported." (PMID 33323975, 2021). "Therefore, it is interesting to note that, in contrast to TXNIP, TRX is upregulated in various cancers." (PMID 33081035, 2020). "Further, TXNIP protein expression was determined in primary mouse xenograft tumors derived from human cancer cell lines and was immunohistochemically absent in all xenograft tumors investigated." (PMID 33081035, 2020). "Finally, analyses of different datasets from the Oncomine database verify upregulation of the TXNIP in tumoral tissues as compared to their normal counterparts in HCC and other common cancers." (PMID 30627326, 2018). "Although previous reports have revealed the role of TXNIP in the regulatory mechanisms of glucose uptake and glucose metabolism in cancer and primary cells, the function of TXNIP in cellular senescence under glucose stress has not been reported." (PMID 30168649, 2018). "An initial screen of different cancer cell lines that are treated with 1,25(OH)2D3 surprisingly showed all the possible options, induction, reduction, and no change in TXNIP levels in response to treatment." (PMID 29534438, 2018). "Thus, developing TXNIP-targeted therapy should be restricted to cancers exhibiting TXNIP downregulation and should aim at normalizing but not at increasing TXNIP activity." (PMID 33846376, 2021). "As we identified that TXNIP was a target of MAGI2-AS3 and results in the reduced expression in of TXNIP in HCC and impaired cancer progression, we suspected that altered MAGI2-AS3 expression may also cause changes in the immune cell populations in the microenvironment of HCC patients." (PMID 34484334, 2021). "At the G1 phase (G1-cell cycle arrest), D-allose induces specific thioredoxin interacting protein (TXNIP) and stabilize p27kip1 protein, which inhibits the cancer cells growth without affecting normal cells." (PMID 35204283, 2022). "The critical role of thioredoxin-interacting protein (TXNIP) in cellular sulfhydryl redox homeostasis and inflammasome activation is already widely known, however, no pan-cancer analysis is currently available." (PMID 35843949, 2022).
cancer (continued). "TXNIP expression was also anti-correlated with MCTs and NHE1 in non-transformed tissues, demonstrating that pH-dependent regulation of MondoA activity at the TXNIP is not restricted to cancer cells." (PMID 30717828, 2019).